C3 (complement C3)
Diseases named in the same sentence as C3 in open-access papers (continued):
Sharing a sentence is not in itself a finding about the gene and the disease.
pancreatic cancer (24 papers, 2010 to 2026). "The expression of complement C3 in pancreatic cancer was described as significantly higher than in normal tissues and was proposed as a diagnostic biomarker of early-stage pancreatic cancer." (PMID 35626021, 2022). "Pathogenic fungi in pancreatic tumor tissues bind Mannose-binding lectin (MBL) to activate the complement C3 cascade and promote pancreatic cancer progression." (PMID 33520714, 2020). "Pathogenic fungi in pancreatic cancer may activate the complement cascade via mannose‐binding lectin (MBL)‐C3 pathway activation, thereby promoting pancreatic cancer development." (PMID 41574027, 2026). "To document the expression of C3 and Malassezia and associated genes in our patient population, we decided to perform studies on paraffin embedded pancreatic cancer biopsies using pancreatic cancer and their normal tissue counterpart samples from the University of New Mexico Tissue Repository." (PMID 37034706, 2023). "To document the expression of C3 and Malassezia and associated genes in our patient population, we decided to perform studies on paraffin embedded pancreatic cancer biopsies using pancreatic cancer and their normal tissue counterpart samples from the University of New Mexico (UNM) Tissue Repository." (PMID 37910468, 2023). "Our data further support the complement system as a potential mediator of these processes, which we tested by injecting murine pancreatic cancer cells into wild-type mice and mice with genetic deletion of the central complement component 3 (C3–/– mice)." (PMID 40198138, 2025). "We subsequently show that complement C3a is involved in the exclusion of NK cells from the TME and the inhibition of the C3a/C3aR axis in a syngeneic mouse model of pancreatic cancer restores NK cell infiltration resulting in tumor growth delay." (PMID 35937458, 2022). "A study in patients with pancreatic cancer revealed that preoperative plasma levels of nine proteins, including complement factors C1q-B, C3 and C4A correlated with the 1-year disease-free survival." (PMID 20877360, 2010). "Thus, we subsequently tested the role of complement activation in cancer-induced muscle pathologies by injecting KPC pancreatic cancer cells into the pancreas of wild-type mice or mice null for the central component of complement 3 (C3)." (PMID 40198138, 2025). "In addition to the known complement activation pathways such as the classical, lectin, and alternative pathways, C3 can also be cleaved into C3a by the enzymatic activity of cathepsins which are upregulated in pancreatic cancer." (PMID 35937458, 2022). "C3 and soluble iC3b have also been suggested as tumor markers for pancreatic cancer." (PMID 31620245, 2019). "In addition, studies have reported increased concentrations of C3, AHSG, and SERPINF1 proteins in the peripheral blood of pancreatic cancer patients." (PMID 37759310, 2023). "Deletion of C3 from the murine host did not impact pancreatic tumor growth or substantially impact the tumor transcriptome, as determined via RNA-Seq of KPC tumors from WT and C3–/– mice." (PMID 40198138, 2025).
influenza (23 papers, 2007 to 2026). An acute viral infection of the respiratory tract, occurring in isolated cases, in epidemics, or in pandemics; it is caused by serologically different strains of viruses (influenzaviruses) designated A, B, and C, has a 3-day incubation period, and usually lasts for 3 to 10 days. "Studies with C3-deficient mice reveal an impaired anti-viral CD4+ T cell response in an influenza infection model and humans with C3-deficiency lack an adequate Th1 response and thus suffer from recurrent infections." (PMID 33808005, 2021). "Influenza-associated acute lung injury (ALI) in A(H5N1)-infected mice has been linked to excessive complement activation with deposition of C3 and C5b-9, and increased expression of complement receptors C3aR and C5aR." (PMID 28884355, 2018). "Similar to previous reports, depletion of C3 in guinea pigs was associated with altered inflammatory cell infiltration to the lungs in response to influenza infection." (PMID 28418930, 2017). "CD8+ T cell responses are critical in the protection against influenza infection, and it is noteworthy that C3 deficiency affects T cell immunity, viral clearance and survival." (PMID 23326231, 2013). "However, studies on C3-knock out mice infected with seasonal influenza virus show that C3 is required for protection against influenza infection, for proper virus clearance, and is associated with changes in cellular infiltration." (PMID 35204727, 2022). "Thus, our observations reiterate the critical importance of C3 during influenza infection, and we surmise increased viral load leading to pneumonia as a possible cause of mortality in the C3−/− mice." (PMID 23326231, 2013). "In this study, we used C3-deficient (C3−/−) mice to show that C3 was critical for survival during influenza infection, and C3 deficiency was associated with attenuated T cell priming in the dLN and reduced development of effector T cell responses in the lung as previously shown." (PMID 23326231, 2013). "However, studies in knockout mice demonstrated that C3 was required for protection from influenza infection, proper viral clearance, and associated with changes in cellular infiltration." (PMID 21408070, 2011). "In our 3D nasal and bronchial models, influenza infection induced intracellular C3 production and C3a release." (PMID 40929365, 2026). "CD103+ DC, a migratory DC subset, can secrete complements C3 and C5, resulting in the induction of T-cell immune responses and virus clearance after influenza infection." (PMID 39221016, 2024). "Fewer CD4 + and CD8 + T-cells were detected in the BALF of these mice, indicating that C3 plays an important role in promoting specific immunity during influenza infection via the induction of T-cell lymphocyte priming and migration." (PMID 38368584, 2024). "In mice, C3 has been shown to play a crucial role in inducing humoral and cellular responses to influenza vaccination." (PMID 35927283, 2022). "The presence of influenza led to an increase of C3 in platelet supernatants but only in those with platelet TLR7 expression as assessed by qPCR or antibody staining." (PMID 30992428, 2019). "Here, we report a novel mechanism by which platelets cross-communicate with neutrophils to mediate the initial intravascular response to influenza infection through C3." (PMID 30992428, 2019). "In mice, complement component C3 is required for protection against influenza and for proper viral clearance." (PMID 30992428, 2019). "Our data demonstrate that platelet-TLR7-driven responses lead to C3 release during influenza infection and consequently, C3 augments the release of DNA from neutrophils and promotes the formation of platelet–neutrophil aggregates which may contribute to influenza-mediated increased risk of MI." (PMID 30992428, 2019). "We first screened plasma isolated from the influenza-infected patients to assess if C3 is released during influenza infection in vivo and we found increased levels of circulating C3 compared to control." (PMID 30992428, 2019).
influenza (continued). "TLR7 specificity is confirmed in murine models lacking the receptor, and platelet depletion models support platelet-mediated C3 and neutrophil-DNA release post-influenza infection." (PMID 30992428, 2019). "Previously it has been shown that C3 deficiency results in enhanced viral spread and impaired recruitment of virus-specific CD4+ and CD8+ effector T cells in the lung during seasonal influenza infection owing to attenuated T cell priming." (PMID 28301559, 2017). "Since only CD103+ DCs showed increased C3 and C5 mRNA expression upon influenza infection, we evaluated the contribution of CD103+ DCs to the observed increase in C3a and C5a levels in the lung during influenza infection." (PMID 23326231, 2013). "In this study, using a model of influenza infection, we demonstrate that complement component C3 is critically required for efficient emigration of DCs from the lung to the dLN." (PMID 23326231, 2013). "This is further supported by our observations in CD103+ DC-depleted langerin-DTR mice which showed deleterious effects on survival and effector T cell responses similar to those observed in C3−/− mice upon influenza infection." (PMID 23326231, 2013). "Among the mDC subsets, only the CD103+ DCs were found to produce the complement components C3 and C5 upon influenza infection and depletion of CD103+ DCs significantly reduced the availability of C3a and C5a in the lungs." (PMID 23326231, 2013). "Upon influenza infection, both the relative and absolute numbers of lung CD103+ DCs and CD11b+ DCs became comparable between C3−/− and WT mice during influenza infection." (PMID 23326231, 2013). "Overall, these studies suggest that C3 is an important host response during influenza infection; potentially by aiding in viral clearance and regulating lung inflammation." (PMID 21408070, 2011). "These experimental results indicate that C3 has a protective role in influenza infection." (PMID 38368584, 2024). "Further investigation of complement C3 levels or dynamic changes in this factor could provide additional support for the use of C3 as a predictor for poor prognoses of patients with severe influenza." (PMID 36647106, 2023). "These selected proteins, such as plasma protease C1 inhibitor, hemopexin, transferrin, complement factor B and complement C3, have been identified as candidate biomarkers of acute respiratory virus infection or exhibited obvious fold changes during influenza infection." (PMID 34867309, 2021). "In addition, complement promotes DC migration independent of inflammatory stimuli (e.g., LPS) during in vivo Influenza infection, as it is hampered in C3−/− mice." (PMID 33767691, 2021). "Our data suggest that platelets contribute to C3 secretion and mediate DNA release from Ly6G-positive cells (mostly neutrophils but may include some eosinophils) during influenza infection." (PMID 30992428, 2019). "We demonstrate an increase in C3 in influenza-infected patients’ plasma." (PMID 30992428, 2019). "Finally, we identified CD103+ DCs as the sole mDC subset capable of secreting C3 and C5 and one of the major source of lung C5a during influenza infection." (PMID 23326231, 2013). "However, among lung DCs, only CD103+ DCs make a significant contribution to lung C5a levels and exclusively produce high levels of C3 and C5 during influenza infection." (PMID 23326231, 2013). "C3 has been shown to be important for eliciting T cell responses and viral clearance during influenza infection in mice, although the impact of C3 deficiency on survival after influenza infection was not well reported." (PMID 23326231, 2013). "Next, we investigated the composition of mDC subsets in the lung and lung dLN at steady state and during the course of influenza infection to test whether the priming defect could be explained by a defect of the mDC network in the lung and dLN of C3−/− mice." (PMID 23326231, 2013).
influenza (continued). "The specific production of C3 and C5 by CD103+ DCs underlines their central role in transporting antigen from the lung to the dLN, allowing the priming of T-cells during the early phase of influenza infection." (PMID 23326231, 2013). "However, the inflammation was exacerbated in the infected C3−/− animals suggesting that C3 plays a protective role during influenza infection." (PMID 21408070, 2011). "Thus, we hypothesized that C3 may be critically involved in the control of the T cell priming function of lung mDCs during influenza infection." (PMID 23326231, 2013). "Given that influenza infection triggered C3 mobilization, also recently described for SARS-CoV-2 and influenza, we measured C3a and C5a levels on the basolateral subnatants." (PMID 40929365, 2026). "Here, the authors show that influenza can be found in human platelets and that platelet engulfment of influenza A results in TLR7-dependent C3 release, which in turn promotes neutrophil-DNA release and formation of platelet-DNA aggregates." (PMID 30992428, 2019). "It will also be necessary to understand C3 regulation as a function of non-pathogenic inflammation and to evaluate if regulation of C3 by inhibitors such as compstatin could attenuate cardiothrombotic events and reduce the risk of influenza-mediated MI." (PMID 30992428, 2019). "In this study, we show that influenza is found in the circulation where it is engulfed and recognized by platelet-TLR7 leading to complement C3 release." (PMID 30992428, 2019). "Our study demonstrates that, during influenza infection, platelets internalize influenza and coordinate a distinct, multifactorial response as a function of their TLR7-mediated C3 release." (PMID 30992428, 2019). "Overall, these data suggest that heightened levels of C3 in bronchoalveolar lavage fluid during H5N1 infection of guinea pigs may contribute to host defense by promoting viral clearance and limiting influenza induced lung pathology." (PMID 28418930, 2017). "However, it is interesting to note that upon influenza infection, CD103+ DCs exclusively produced high levels of C3 and C5, yielding activation fragments C3a and C5a." (PMID 23326231, 2013). "However, absolute numbers of both CD103+ DCs and CD11b+ DCs were significantly decreased in C3−/− mice, suggesting a decreased migration capacity of CD103+ DCs and CD11b+ DCs at both steady state and at all time points tested after influenza infection." (PMID 23326231, 2013). "However, at least in Influenza infection, maturation of migratory DCs is not dependent on complement C3 or its cleavage products." (PMID 33767691, 2021). "In order to understand whether a strong inflammatory signal is able to overcome the defective signaling on mDCs due to the lack of C3, we administered LPS intratracheally shortly after influenza infection and then evaluated mDC migration in C3−/− mice." (PMID 23326231, 2013). "No modulation of C3 and C5 mRNA expression was observed in CD11b+ DCs after influenza infection." (PMID 23326231, 2013). "Furthermore, we observed that C3 does not play a costimulatory role on lung mDCs as the expression of maturation markers and the priming ability of mDCs from the dLN were comparable between WT and C3−/− mice during influenza infection." (PMID 23326231, 2013).
diabetic nephropathy (22 papers, 2019 to 2026). "In diabetic patients, elevated glomerular and tubular expression of C3 and Factor B—the two components of the alternative pathway C3 convertase C3bBb that cleaves C3 to C3a and C3b—has been associated with overt diabetic nephropathy." (PMID 31428128, 2019). "This possibility is confirmed by the recent observation that among patients with diabetic nephropathy, the presence of deposits of C3 activation products in kidney biopsy was associated with lower renal function and more severe tubular and glomerular damage." (PMID 31428128, 2019). "Moreover, the role of complement component C3 in diabetic nephropathy and retinopathy has been implicated, and C3 N-glycome was found to be altered in young T1D patients." (PMID 37293493, 2023). "Researchers have suggested that complement C3 is activated in podocytes and renal tubules in animal models of diabetic nephropathy, causing fibrosis and renal dysfunction, and that administration of C3 receptor blockers protects diabetic nephropathy podocytes from injury." (PMID 34424825, 2021). "In this context, glycated complement components C3 and C4 are observed in the early stages of diabetic nephropathy." (PMID 38069385, 2023). "Although the relevance of CXCL6 has been validated in in vitro using a human podocyte cell line and in kidney biopsies and resections, the role of C3 in remains poorly characterized in kidney tissue from patients with diabetic nephropathy." (PMID 36659918, 2023). "The role of B cells in diabetic nephropathy can be furtherly accelerated by their influence on macrophage activation, in which macrophages possess receptors for Fc fragment of IgG (FcRs), C3 protein, and AGEs (receptor for AGEs-RAGE)." (PMID 33478014, 2021). "Notably, G-Hes supplementation considerably decreased the complement component C3 at the mRNA and protein levels in the glomeruli and ameliorated glomerular and mesangial matrix expansion in diabetic nephropathy." (PMID 39940240, 2025). "Furthermore, increased C3 concentrations in renal tissue seem to be in a relation with diabetic nephropathy, as glomerular deposition of activated C3 was observed in several animal studies." (PMID 37293493, 2023). "Baseline characteristics of diabetic nephropathy stratified by glomerular C3 deposits." (PMID 35711407, 2022).
membranous nephropathy (22 papers, 2014 to 2026). "In another approach, the siRNA target was a complement factor (C3) for the treatment of membranous nephropathy." (PMID 38489367, 2024). "Immunofluorescence microscopy demonstrates typical granular peripheral capillary wall deposition of IgG and C3 that is also observed in human membranous nephropathy." (PMID 37628958, 2023). "A renal biopsy revealed EXT1-positive, PLA2R/THSD7A-negative, membranous nephropathy with IgG and C3 deposition." (PMID 33655949, 2021). "C5b-9 colocalized with immune deposits containing IgG, C3, and sometimes C1q and C4 in the capillary wall in all stages of primary membranous nephropathy, except for stage I according to one report." (PMID 33643288, 2020). "In patients with membranous nephropathy and gout, granular deposits of IgG, C3 and renal tubular epithelium antigen were observed in the glomerular capillary wall." (PMID 30935368, 2019). "Immunohistochemical staining revealed diffuse capillary loop granular deposition of IgG, C1q and C3 and electron microscopy confirmed membranous nephropathy." (PMID 24902943, 2014). "The IgG and C3 are some of the biomarkers of that indicate membranous nephropathy." (PMID 39759600, 2024). "Additionally, there is also evidence of alternative pathway activation in primary membranous nephropathy as supported by genetic evidence for the deposition of PLA2R antibody, C3, and C5b-9 in patients with MBL deficiency and via production of antibodies targeting CFH." (PMID 38895123, 2024). "Finally, in a murine model of complement-dependent injury of the glomerular microvasculature resembling human membranous nephropathy, daily subcutaneous injections of resveratrol upregulated HO-1 and significantly reduced glomerular C3 deposition and production of reactive oxygen species." (PMID 31193778, 2019). "Renal biopsy revealed membranous glomerulonephritis along with positive DIF showing IgG and C3 deposition." (PMID 42083672, 2026). "Biopsy sample showed two glomeruli with mesangial expansion and thickened glomerular basement membrane (GBM) on light microscopy, a pattern masquerading as membranous nephropathy stage III-IV, while IgG and C3 were 1-2+ on GBM and mesangium in immunofluorescence." (PMID 37899889, 2023). "Rather, the lectin and alternative pathways are activated, given that C3, C4, FH, FB, and MBL, but not C1q, affect the risk of membranous nephropathy and are generally present in the subepithelial immune deposits." (PMID 33643288, 2020).